REL (REL proto-oncogene, NF-kB subunit)
Description:
Proto-oncogene that may play a role in differentiation and lymphopoiesis. NF-kappa-B is a pleiotropic transcription factor which is present in almost all cell types and is involved in many biological processed such as inflammation, immunity, differentiation, cell growth, tumorigenesis and apoptosis. NF-kappa-B is a homo- or heterodimeric complex formed by the Rel-like domain-containing proteins RELA/p65, RELB, NFKB1/p105, NFKB1/p50, REL and NFKB2/p52. The dimers bind at kappa-B sites in the DNA of their target genes and the individual dimers have distinct preferences for different kappa-B sites that they can bind with distinguishable affinity and specificity. Different dimer combinations act as transcriptional activators or repressors, respectively. NF-kappa-B is controlled by various mechanisms of post-translational modification and subcellular compartmentalization as well as by interactions with other cofactors or corepressors. NF-kappa-B complexes are held in the cytoplasm in an inactive state complexed with members of the NF-kappa-B inhibitor (I-kappa-B) family. In a conventional activation pathway, I-kappa-B is phosphorylated by I-kappa-B kinases (IKKs) in response to different activators, subsequently degraded thus liberating the active NF-kappa-B complex which translocates to the nucleus. The NF-kappa-B heterodimer RELA/p65-c-Rel is a transcriptional activator.
Synonyms: I-Rel; c-Rel; HIVEN86A; IMD92
Tractability: PROTAC: ubiquitination databases record sites on it; its protein half-life has been measured.
Target class: Transcription factor
Gene: Protein-coding gene on chromosome 2 (60,881,491 to 60,931,612, forward strand). Ensembl gene ENSG00000162924.
Subcellular location: Nucleus
Pathways (Reactome):
Immune System: Activation of NF-kappaB in B cells
Gene Ontology:
Molecular function: DNA-binding transcription activator activity, RNA polymerase II-specific; protein binding; RNA polymerase II cis-regulatory region sequence-specific DNA binding; DNA-binding transcription factor activity; DNA-binding transcription factor activity, RNA polymerase II-specific; DNA binding; sequence-specific DNA binding
Biological process: negative regulation of gene expression; negative regulation of interferon-beta production; positive regulation of canonical NF-kappaB signal transduction; positive regulation of transcription by RNA polymerase II; canonical NF-kappaB signal transduction; inflammatory response; innate immune response; non-canonical NF-kappaB signal transduction; response to cytokine; negative regulation of cytokine production; regulation of DNA-templated transcription
Cellular component: nucleus; chromatin; cytosol; NF-kappaB complex; nucleoplasm; cytoplasm
Genetic constraint (gnomAD): Loss-of-function variants: 9 observed, 37.74 expected, observed/expected ratio (o/e) 0.24, 90% interval 0.14 to 0.42. The upper end of that interval is the gene's LOEUF score, 0.42, which puts it in group 1 of 6, group 1 being the genes least tolerant of losing a copy. Missense variants: 497 observed, 616.43 expected, observed/expected ratio (o/e) 0.81, 90% interval 0.75 to 0.87. Synonymous variants: 202 observed, 215.01 expected, observed/expected ratio (o/e) 0.94, 90% interval 0.84 to 1.06.
Gene-disease validity (ClinGen):
ClinGen rates the evidence that REL causes each of these diseases.
immunodeficiency 92 (autosomal recessive): Moderate. An autosomal recessive primary immunodeficiency characterized by the onset of recurrent infections in infancy or early childhood.
Homologues: Orthologues: chimpanzee REL (99% identical), macaque REL (98% identical), rabbit REL (86% identical), dog REL (86% identical), pig REL (86% identical), guinea pig REL (81% identical), mouse Rel (76% identical), rat Rel (76% identical), zebrafish rel (45% identical), tropical clawed frog rel (41% identical), Drosophila melanogaster dl (28% identical), Drosophila melanogaster Dif (25% identical). Paralogues in human: RELA (36% identical), NFKB1 (29% identical), RELB (27% identical), NFKB2 (27% identical).
Diseases named in the same sentence as REL in open-access papers:
REL is named in the same sentence as 171 diseases in open-access papers, as found by Europe PMC text mining. Sharing a sentence is not in itself a finding about the gene and the disease. The quoted sentences say what the papers report.
lymphoma (29 papers, 2011 to 2025). A malignant (clonal) proliferation of B- lymphocytes or T- lymphocytes which involves the lymph nodes, bone marrow and/or extranodal sites. "Amplifications of REL in genome, which are often associated with elevated levels of nuclear c-Rel protein, have been detected in large portion of lymphoma patients." (PMID 38495491, 2024). "In conclusion, through the work of multiple groups over many years a strong case has been made for an association of genetic alterations affecting the REL gene locus both with human lymphoma and autoimmunity." (PMID 31277480, 2019). "8, 18, 19, 20 Moreover, genomic and cytogenetic studies of human lymphomas have shown gains of chromosome 2p13, which encodes the REL gene." (PMID 26522720, 2016). "As an example, a small molecule c-REL inhibitor showed activity against human lymphoma cells in a xenograft model (although, at least in mice, the drug also targets the RELA subunit)." (PMID 36289712, 2022). "REL gene amplifications, leading to increased REL protein expression, have been found in several types of lymphoma, including DLBCL and Hodgkin lymphoma." (PMID 34440093, 2021). "It has been reported that REL gene amplification in lymphoma leads to an increased expression of REL protein, as well as a C‐terminal truncated p100 protein that lacks the ANK repeat inhibitory sequence." (PMID 34977871, 2021). "Together, it emerges that in the majority of analyzed lymphoma cases the BCL11A gene is co-amplified with the REL gene." (PMID 31277480, 2019). "In spite of the pervasive evidence for an oncogenic role of c-Rel in lymphoma functional analyses investigating the elusive roles of REL gene locus amplification and aberrant splicing are missing to date, mostly due to the lack of suitable in vivo models." (PMID 31277480, 2019). "While all three analyses of largely overlapping lymphoma samples agree that gain of REL is a frequent genomic alteration in DLBCL, there is a discrepancy between the reported subgroup frequency." (PMID 31277480, 2019). "We then focus on the frequent occurrence of REL gene locus gains and amplifications in human B cell lymphoma and provide an overview of reported gene locus aberrations in relevant human lymphoma subtypes." (PMID 31277480, 2019). "c-REL amplification was limited to 6/22 GI DLBCL including the large cell component of 2/9 composite small cell/large cell lymphomas, and c-Rel protein expression was found in the large cell compartment of composite lymphomas." (PMID 29057015, 2017). "Consistent with previous studies on lymphomas, we identified REL and BCL11A located at 2p16.1, and BCL2 at 18q21.3 being among the genes, whose expression was linked with copy number gains." (PMID 24625556, 2014). "Besides these hard-wired genetic alterations involving the REL gene locus, c-Rel protein expression in lymphoma can also be altered through aberrant splicing." (PMID 31277480, 2019). "The 7 c-REL amplified lymphomas all showed a nuclear and a cytoplasmic c-Rel staining." (PMID 28729720, 2017). "The majority of distinct CNVs we observed were hallmarks of the respective lymphoma subtype, e.g., 8q and 11q deletions in the T-PLL, a 13q14 deletion in the case 5 CLL, and the gains of JAK2/PD-L1/PD-L2 and REL in the HL of cases 1 and 4, respectively." (PMID 40404986, 2025). "In particular, recurrent gain/amplificationof the 2p15-p16.1 locus, where REL, BCL11A, PAPOLG,PUS10, and USP34 genes reside, is a common observationin different lymphoma types including classical Hodgkinlymphoma and transformedfollicular lymphoma." (PMID 31410080, 2019). "FISH analyses using BAC clones covering lymphoma breakpoints (BCL2, BCL6, BCL11A, CCND1, CCND3, IG-H/K/L, JAK2, LMO2, MYC, PAX5, REL) all tested normal, excluding rearrangements at these loci." (PMID 26599546, 2015).
lymphoma (continued). "c-REL amplification was limited to 6/22 large cell MZBL including the large cell component of 2/9 composite small cell/large cell lymphomas, and c-Rel protein expression was found in the large cell compartment of composite lymphomas." (PMID 28729720, 2017). "Fusion or gain of REL, a member of the NF-κB pathway, and BCL11A was reported to be enriched in transformed lymphoma, and this may be a genomic marker for disease progression to clinically more aggressive forms." (PMID 27835906, 2016). "Lymphoma cells could then locate to another environment, where an absence of signals activating c-Rel transcriptional activity renders the presence of REL gain irrelevant." (PMID 31277480, 2019). "However, the nuclear and cytoplasmic staining pattern was not limited to the amplified lymphomas but also detected in 28 lymphomas without c-REL amplification (3 only nuclear; 7 only cytoplasmic; 18 cytoplasmic and nuclear)." (PMID 28729720, 2017).
psoriasis (19 papers, 2012 to 2025). An autoimmune condition characterized by red, well-delineated plaques with silvery scales that are usually on the extensor surfaces and scalp. "Alterations in the REL gene have been linked to autoimmune conditions such as rheumatoid arthritis, psoriasis, celiac disease, and certain hematological malignancies." (PMID 40843700, 2025). "The REL SNP rs702873 has been identified as a susceptibility locus in psoriasis, however, the mechanism in which this SNP is able to alter c-Rel expression or function is unclear." (PMID 39586195, 2024). "In fact, genome-wide association studies reported associations of single nucleotide polymorphisms (SNPs) within the REL gene locus for human diseases with immunological etiology, including rheumatoid arthritis, psoriasis, ulcerative colitis and celiac disease." (PMID 31277480, 2019). "Genome-wide studies have also found that REL locus was associated with psoriasis, rheumatoid arthritis, ulcerative colitis and Hodgkin’s lymphoma." (PMID 27059500, 2016). "These sub-groups correlated with the composition of the inflammatory infiltrate, but were only weakly associated with increased risk allele frequency at some psoriasis susceptibility loci (e.g., REL, TRAF3IP2 and NOS2)." (PMID 22479649, 2012). "However, further studies are needed to investigate the clinical outcomes of patients with REL SNPs which increase psoriasis susceptibility and c-Rel protein function." (PMID 39586195, 2024). "Indeed, the intronic rs13031237 SNP in the REL gene was associated with susceptibility to rheumatoid arthritis and psoriasis." (PMID 27059500, 2016). "A meta-analysis identified 11 susceptibility loci shared between psoriasis and IBD, but only four—IL23R, IL12B, REL, and TYK2—showed strong overlap for CD, suggesting weaker genetic linkage compared with UC." (PMID 41153620, 2025). "For some loci, this is a stronger effect size (TRAF3IP2, REL, FBXL19); for others, different genetic variants at the same locus predispose to psoriasis and PsA (IL23R) whereas other loci appear specifically associated with PsA (HLA B27, 5q31 locus)." (PMID 26255310, 2016). "Nevertheless, 7 of the PP-increased DEGs were associated with psoriasis susceptibility loci (LCE3D, IFIH1, GRHL3, IL12B, PRSS53, REL and NOS2), and 1 PP-decreased DEG was near a psoriasis susceptibility locus (SDC4)." (PMID 24260178, 2013). "For example, REL which is highly connected in CytReg, but not in TRRUST, has been associated with rheumatoid arthritis, psoriasis, and Hodgkin's lymphoma but not with diseases unrelated to the immune system." (PMID 30184180, 2018). "We searched for transcription factor binding motifs intersected by psoriasis SNPs interacting with active gene promoters using the tool SNP2TFBS and discovered several significantly enriched factors, with the greatest enrichment found for REL, which is itself a candidate gene in the 2p16.1 locus." (PMID 32366252, 2020).
breast cancer (18 papers, 2008 to 2025). A primary or metastatic malignant neoplasm involving the breast. "The gene NFKB1 was found to be mutated and elevated in breast cancer, while REL is suggested to play some role as the NFKB genes belong to the REL family." (PMID 28607444, 2017). "Comparison of human mammary epithelial cells (HMECs) to mesenchymal claudin-low SUM159 breast cancer cells revealed decreases in REL transcript and increases in RELB transcript in SUM159s relative to HMECs." (PMID 32859943, 2020). "In 2000, Cogswell and colleagues revealed the induction of mammary tumors by c-REL expression in mouse models of breast cancer." (PMID 29673141, 2018). "Many studies have revealed a relation between c-REL subunit and development of breast cancer and non-small cell lung cancer and the role of the p50–p65 subunits of NF-κB in the carcinogenesis of the breast." (PMID 18928570, 2008).
melanoma (17 papers, 2012 to 2025). A malignant, usually aggressive tumor composed of atypical, neoplastic melanocytes. "As a recent example, specifically ablating c-REL function in murine Treg cells delayed melanoma growth by impairing Treg-mediated immunosuppression, and potentiated the effects of anti-PD-1 immunotherapy." (PMID 30380749, 2018). "Thus, RAB6B, REL and WHSC1L1, as identified by our analysis, may represent additional oncogenes for melanoma." (PMID 22295108, 2012).
B-cell lymphoma (15 papers, 2008 to 2025). "It is noteworthy that the REL gene locus is not only implicated in human B cell lymphoma, but also in autoimmunity." (PMID 31277480, 2019). "The REL gene, encoding the NF-κB subunit c-Rel, is frequently amplified in B-cell lymphoma and functions as a tumour-promoting transcription factor." (PMID 26522720, 2016). "Furthermore, c-Rel is implicated in human B cell lymphoma through the frequent occurrence of REL gene locus gains and amplifications." (PMID 31277480, 2019). "A gain of a chromosomal area including the REL genomic locus is a highly frequent event in GC-derived human B cell lymphomas." (PMID 31277480, 2019). "Nevertheless, REL gains and amplifications are an even more frequent characteristic at the transformed stage of this human B cell lymphoma subtype (tFL)." (PMID 31277480, 2019). "The studies discussed in this review highlight the remarkably frequent gains and amplifications of the human gene locus 2p16.1 containing the REL gene in several human B cell lymphoma subtypes." (PMID 31277480, 2019). "Our data suggest that CM101-like compounds that covalently modify REL to inhibit its DNA-binding activity represent a promising approach for the treatment of cancers (especially B-cell lymphomas) whose survival depends on active nuclear REL." (PMID 25915462, 2015). "It harbored REL, a member of the NF-κB family of transcription factors, which was found to be amplified in primary mediastinal B-cell lymphoma." (PMID 19759907, 2009). "Chromosomal gains including the REL locus were also found in three additional types of B cell lymphoma, namely nodular lymphocyte predominant Hodgkin lymphoma (NLPHL), T cell/histiocyte-rich large B cell lymphoma (THRLBCL) and B cell chronic lymphocytic leukemia (CLL)." (PMID 31277480, 2019). "Furthermore, we summarize publications analyzing c-Rel expression and protein localization in these human B cell lymphomas and discuss the co-amplification of BCL11A with REL." (PMID 31277480, 2019). "Direct inhibitors of REL may be useful for treating B-cell lymphomas in which REL is active, and may inhibit B-lymphoma cell growth at doses that do not affect some immune-related responses in normal cells." (PMID 25915462, 2015). "However, amplification of c-REL was observed in a broad range of human B-cell lymphomas." (PMID 28767691, 2017). "Here, we applied database mining using the COSMIC database and observed profound overexpression of c-REL in various human tumors, which is in accordance to the observed amplification of c-REL in human B-cell lymphomas." (PMID 28767691, 2017).
Hodgkins lymphoma (14 papers, 2011 to 2025). A heterogeneous group of malignant lymphoid neoplasms of B-cell origin characterized histologically by the presence of Hodgkin and Reed-Sternberg (HRS) cells in the vast majority of cases. "In classical Hodgkin lymphoma, non-Hodgkin lymphoma and diffuse large B-cell lymphoma, BCL11A is found to be coamplified with the proto-oncogene REL and is associated with enhanced c-Rel expression." (PMID 39857257, 2025). "The REL locus at the chromosomal position 2p16.1-15 is amplified in Hodgkin’s lymphoma (~46%) and diffuses large B cell lymphoma (DLBCL) (~15%)." (PMID 29562713, 2018). "In 1999, Krappmann and colleagues described a constitutive NF-κB-activity with NF-κB-complexes containing RELA and c-REL in malignant cells derived from Hodgkin’s disease." (PMID 28767691, 2017). "For example, REL gene amplifications occur in diffuse large B-cell lymphoma (DLBCL), Hodgkin’s lymphoma and follicular lymphoma, and overexpression of wild-type and mutant forms of human REL can transform lymphoid cells in culture." (PMID 25915462, 2015). "Increased c-Rel expression has been observed in Hodgkin lymphoma where the REL locus was found to be translocated to a position near the light chain enhancer, or alternatively by integration of an EBV genome near to the c-Rel encoding region." (PMID 29562713, 2018).
diffuse large B-cell lymphoma (13 papers, 2009 to 2025). "In the first study, a gene homologous to the REL transcription factors, later designated as NFKB2, was cloned from a translocation breakpoint in a diffuse large B-cell lymphoma (DLBCL) case." (PMID 36289712, 2022). "However, another study has suggested that the amplification of the 2p region is not always related to elevated expression of REL in diffuse large B-cell lymphoma (DLBCL)." (PMID 29315242, 2018).
Autoimmunity (11 papers, 2011 to 2025). The occurrence of an immune reaction against the organism's own cells or tissues. "Moreover, genetic variants within the REL locus have been associated with inflammatory diseases or autoimmunity in Europeans." (PMID 27059500, 2016). "REL (OR = 1.66; p = 0.034) is a subunit of NF-kB complex, implicated in T cell differentiation and it appears to be a key molecule regulating inflammation and the switch from tolerance to autoimmunity." (PMID 22087237, 2011). "Upon TCR activation, ubiquitin ligase PELI1 negatively regulates c-REL through K48-linked ubiquitylation, and genetic deficiency in PELI1 causes hyperactivation of T cells and development of autoimmunity." (PMID 26038114, 2015).
prostate carcinoma (11 papers, 2005 to 2025). A carcinoma that arises from epithelial cells of the prostate gland. "In our study, Ang1–7 decreased the mRNA level of RELA, RELB and REL gene, thus Ang1–7 might potentially contributes to the suppression of prostate cancer." (PMID 30361641, 2018).
rheumatoid arthritis (11 papers, 2011 to 2025). A chronic, systemic autoimmune disorder characterized by inflammation in the synovial membranes and articular surfaces. "Polymorphisms of REL (c-Rel) have been shown to segregate with both psoriatic arthritis and rheumatoid arthritis, and altered expression has been noted in other autoimmune diseases." (PMID 29686669, 2018). "The specific suppression of circ_0088036 hindered the growth of RA-FLS cells and triggered programmed cell death, indicating its involvement in the development of rheumatoid arthritis through the miR-1263/REL/NF-κB pathway." (PMID 39530095, 2024).
Parkinson disease (10 papers, 2015 to 2023). A progressive degenerative disorder of the central nervous system characterized by loss of dopamine producing neurons in the substantia nigra and the presence of Lewy bodies in the substantia nigra and locus coeruleus. "REL promotes survival and apoptosis resistance in hippocampal neurons and its knockout promotes a Parkinson's disease-like phenotype." (PMID 37937284, 2023).